RNU6-137P (RNA, U6 small nuclear 137, pseudogene)
Gene: Small nuclear RNA gene on chromosome 2 (42,712,740 to 42,712,847, forward strand). Ensembl gene ENSG00000200550.
Homologues: Orthologues: chimpanzee U6 (97% identical), macaque U6 (94% identical), guinea pig U6 (87% identical), rat U6 (87% identical), rabbit U6 (84% identical), dog U6 (83% identical), dog U6 (82% identical), rat LOC120093297 (80% identical). Paralogues in human: RNU6-31P (89% identical), RNU6-949P (89% identical), RNU6-1060P (88% identical), RNU6-24P (88% identical), RNU6-480P (88% identical), RNU6-1270P (87% identical), RNU6-17P (87% identical), RNU6-18P (87% identical), RNU6-19P (87% identical), RNU6-21P (87% identical), RNU6-22P (87% identical), RNU6-33P (87% identical), and 1288 more.